RPH3A (rabphilin 3A)
Diseases named in the same sentence as RPH3A in open-access papers:
RPH3A is named in the same sentence as 40 diseases in open-access papers, as found by Europe PMC text mining. Sharing a sentence is not in itself a finding about the gene and the disease. The quoted sentences say what the papers report.
Central diabetes insipidus (3 papers, 2016 to 2023). A form of diabetes insipidus related to a failure of vasopressin (AVP) release from the hypothalamus. "Recently, we have reported that rabphilin-3A, a rab3a effector protein, might be a major autoantigen in infundibulo-neurohypophysitis (LINH), which causes central diabetes insipidus (CDI) due to insufficient AVP secretion, and autoantibodies against rabphilin-3A might be diagnostic markers for LINH." (PMID 27732637, 2016).
dementia (3 papers, 2017 to 2025). Loss of intellectual abilities interfering with an individual's social and occupational functions. "A study shows that loss of RPH3A functions contributes to dementia severity, cholinergic differentiations, and increased β-amyloid concentrations." (PMID 41153414, 2025). "Recently, it was experimentally shown that reduction of rabphilin-3A in Alzheimer’s disease correlates with dementia severity and amyloid beta accumulation." (PMID 28178937, 2017).
Dyskinesia (3 papers, 2022 to 2023). A movement disorder which consists of effects including diminished voluntary movements and the presence of involuntary movements. "Another interesting target from the current proteomics dataset is Rabphilin-3A (RPH3A), which is implicated in levodopa-induced dyskinesia and is dysregulated in PD." (PMID 36831023, 2023). "RPH3A was also shown to be a novel target for levodopa-induced dyskinesias." (PMID 36138874, 2022).
germinoma (3 papers, 2022 to 2025). A malignant germ cell tumor arising in the central nervous system. "The presence of anti-rabphilin-3A antibodies was first demonstrated in a patient with a biopsy-proven germinoma." (PMID 37697216, 2023). "Particularly, among the seven patients definitively diagnosed by biopsy, two of the three with LPH and the one with germinoma were positive for anti-rabphilin-3A antibodies." (PMID 35292721, 2022). "Further studies are needed to clarify the significance of the presence of anti-rabphilin-3A antibodies in germinomas." (PMID 35292721, 2022). "In addition, anti-rabphilin-3A antibodies were found in one germinoma of four biopsy-proven cases with sellar/suprasellar masses, including one germinoma, one craniopharyngioma, and two Rathke cleft cysts." (PMID 37697216, 2023). "Interestingly, one patient of pathologically proven germinoma (Case 13) was positive for anti-rabphilin-3A antibodies, representing the first case of biopsy-proven germinoma with anti-rabphilin-3A antibodies positivity." (PMID 35292721, 2022). "Taken together, germinoma tumor cells or a certain degree of inflammation in the posterior pituitary may promote generation of anti-rabphilin-3A antibodies." (PMID 35292721, 2022). "We are the first to demonstrate the presence of anti-rabphilin-3A antibodies in patients with biopsy-proven LPH and germinoma." (PMID 35292721, 2022). "We also confirm the positivity of anti-rabphilin-3A antibodies in two patients with biopsy proven LPH and one patient with biopsy proven germinoma by immunocytochemical analysis." (PMID 35292721, 2022). "A recent case report including 2 young patients with idiopathic AVP-D who tested negative for anti-rabphilin-3A antibody and were subsequently found to have a germinoma 1.5 years later." (PMID 39726668, 2025). "We aimed to confirm the usefulness of measuring anti-rabphilin-3A antibodies in the diagnosis of non-lymphocytic lesions, including germinoma with CDI without an obvious tumor in sellar or suprasellar regions." (PMID 37697216, 2023). "Though further research is required to corroborate the finding that germinoma can be diagnosed based on elevated CSF PLAP without biopsy, a negative test for anti-rabphilin-3A antibody would help this diagnostic process to exclude LINH." (PMID 37697216, 2023). "In this report, all 34 biopsy-proven samples from sellar/suprasellar masses, including five germinomas, were negative for anti-rabphilin-3A antibodies, yielding a specificity of 100% for distinguishing sellar/suprasellar masses." (PMID 37697216, 2023). "Of these 15 patients, anti-rabphilin-3A antibodies were positive in nine patients, including four of five with LINH, three of four with LPH, one of two with sarcoidosis, and the one patient with germinoma." (PMID 35292721, 2022). "Anti-rabphilin-3A antibodies evaluated by western blotting were positive in nine patients: four of the five with LINH, three of four with LPH, one of two with sarcoidosis and the one patient with germinoma." (PMID 35292721, 2022). "Furthermore, a negative test for anti-rabphilin-3A antibody, a useful marker of LINH, elevates the risk for the development of non-lymphocytic lesions, including germinoma in young patients with CDI." (PMID 37697216, 2023). "Our data suggest that the absence of anti-rabphilin-3A antibodies in young patients clinically diagnosed with idiopathic CDI may increase the probability of the development of non-lymphocytic lesions, including germinoma." (PMID 37697216, 2023).
Huntington disease (3 papers, 2017 to 2022). Huntington disease (HD) is a rare neurodegenerative disorder of the central nervous system characterized by unwanted choreatic movements, behavioral and psychiatric disturbances and dementia. "Recent studies have found that loss of Rph3A is associated with Alzheimer’s and Huntington’s disease, suggesting a crucial role of Rph3A in synaptic function." (PMID 36173100, 2022). "Rph3A is involved in the development of neurodegenerative diseases, such as Huntington's disease, Alzheimer's disease, and pharmacological dyskinesias." (PMID 35467084, 2022). "For example, in a transgenic mouse model of Huntington's disease (R6/1), deletion of Rph3A may be responsible for synaptic dysfunction." (PMID 35467084, 2022). "For example, increased RPH3A, Ras-related protein Rab-3A promotes synaptic vesicle traffic and fusion while aberrant interaction with alpha-synuclein leads to aggregates found in Huntington chorea." (PMID 28423529, 2017).
lymphocytic hypophysitis (3 papers, 2022 to 2025). "Therefore, anti-rabphilin-3A antibodies are relatively common in LINH or lymphocytic hypophysitis, and may be valuable for differentiating between CDI etiologies." (PMID 37697216, 2023). "Thus, we believe that anti-rabphilin-3A antibody may be a useful, noninvasive diagnostic marker not only for LINH but also for lymphocytic hypophysitis in general; when LINH is suspected, an anti-rabphilin-3A antibody test should be performed before proceeding to biopsy." (PMID 39726668, 2025). "This is the first report of the presence of anti-rabphilin-3A antibodies in LPH, a subtype of lymphocytic hypophysitis that affects both of the anterior and posterior pituitary gland and causes CDI." (PMID 35292721, 2022). "Therefore, to date, among 38 biopsy-proven samples from sellar/suprasellar masses not due to lymphocytic hypophysitis, anti-rabphilin-3A antibodies have been reported in only one case." (PMID 37697216, 2023).
Cerebral ischemia (2 papers, 2022). Restriction of arterial blood supply to the brain associated with insufficient oxygenation to support the metabolic requirements of the tissue. "The expression of RPH3A was increased in brain penumbra tissue of a rat cerebral ischemia-reperfusion model." (PMID 36138874, 2022). "The aim was to study the role of Rph3A in neuronal injury induced by cerebral ischemia‐reperfusion." (PMID 35467084, 2022). "In the present study, we aimed to explore the association of Rph3A with CIRI, and observe the Rph3A protein levels, mRNA levels and subcellular location to investigate the role of Rph3A in the pathological process of cerebral ischemia‐reperfusion as well as the mechanism underlying it." (PMID 35467084, 2022). "Although Rph3A has been studied for decades, studies have not directly measured the changes in protein levels and mRNA levels of Rph3A induced by cerebral ischemia‐reperfusion." (PMID 35467084, 2022).
cognitive decline (2 papers, 2020 to 2025). "RPH3A, another downregulated gene involved in synaptic signaling, correlates with cognitive decline and is specifically downregulated by amyloid-β." (PMID 32255787, 2020). "Therefore, the downregulation of VGF, NEUROD6, KCNF1, KCNE5, CRH, and RPH3A may contribute to the cognitive decline observed in elderly individuals with AD." (PMID 39834440, 2025).
COVID-19 (2 papers, 2021 to 2025). A disease caused by infection with severe acute respiratory syndrome coronavirus 2. "One study concluded that positivity for anti-rabphilin-3A antibodies suggested that COVID-19-associated pituitary dysfunction was hypophysitis that involved an abnormal immune mechanism." (PMID 41347136, 2025).
epilepsy (2 papers, 2025). A brain disorder characterized by episodes of abnormally increased neuronal discharge resulting in transient episodes of sensory or motor neurological dysfunction, or psychic dysfunction. "A number of THC target DEGs were also associated with synaptic signaling in the brain, and the onset of epilepsy and intellectual deficits, including RPH3A, KCNQ5, and FRY." (PMID 41402937, 2025). "Moreover, gain-of-function variants in RPH3A and UNC13A have been detected in individuals with phenotypes ranging from epilepsy and developmental delay to ASD." (PMID 40649845, 2025).
Parkinson disease (2 papers, 2022). A progressive degenerative disorder of the central nervous system characterized by loss of dopamine producing neurons in the substantia nigra and the presence of Lewy bodies in the substantia nigra and locus coeruleus. "It has been shown that Rph3A expression at striatal synapses and its interaction with GluN2A‐containing NMDAR are increased in a rat model of Parkinson's disease." (PMID 35467084, 2022).
breast carcinoma (1 paper, 2024). "Neutrophil polarization has been associated with lung metastasis in triple-negative breast cancer, while RPH3A plays a critical role in neutrophil polarization and may contribute significantly to breast cancer metastasis." (PMID 38300336, 2024).
diabetes (1 paper, 2014). "We hypothesize that these genetic backgrounds of RPH3A and ACE-I interact with the BP values and/or the presence of diabetes for the risk to develop microalbuminuria." (PMID 24918908, 2014).
diabetic ketoacidosis (1 paper, 2023). The metabolic condition resulted from uncontrolled diabetes mellitus, in which the shift of acid-base status of the body toward the acid side because of loss of base or retention of acids other than carbonic acid is accompanied by the accumulation of ketone bodies in body tissues and fluids. "Anti-rabphilin-3A antibodies were detected in patients with LINH-associated pregnancy or diabetic ketoacidosis." (PMID 37697216, 2023).
germ cell tumor (1 paper, 2025). A benign or malignant, gonadal or extragonadal neoplasm that originates from germ cells. "In 2022, a patient with a pathologically diagnosed germ cell tumor and positivity for anti-rabphilin-3A antibody was reported." (PMID 39726668, 2025).
glioma (1 paper, 2022). A benign or malignant brain and spinal cord tumor that arises from glial cells (astrocytes, oligodendrocytes, ependymal cells). "Among the model component genes, the overexpression of RPH3A has great potential for its anti-cancer effect on Glioma." (PMID 36138874, 2022). "Several assays were used to detect RPH3A’s role in Glioma cells, including CCK-8, colony formation, wound healing, and transwell migration assay." (PMID 36138874, 2022).
intracranial germinoma (1 paper, 2022). "Among the seven patients definitively diagnosed by pituitary lesion biopsy, anti-rabphilin-3A antibodies were positive in two of the three with LPH (Cases 6 and 12) and in the one with intracranial germinoma (Case 13)." (PMID 35292721, 2022). "Among 15 CDI patients, the positive anti-rabphilin-3A antibodies were found in 4 of 5 LINH cases, 3 of 4 lymphocytic panhypophysitis (LPH) cases, one of 2 sarcoidosis cases, and one intracranial germinoma case, respectively." (PMID 35292721, 2022).
ischemic stroke (1 paper, 2022). A stroke disorder caused by obstruction of blood flow to the brain, due to thrombotic (local blood clot formation) or embolic (due to a blood clot or other material traveling from another site) event. "We explored the role and possible mechanisms of Rph3A in reperfusion by means of in vitro and in vivo ischemic stroke models." (PMID 35467084, 2022). "To explore the role of Rph3A in ischemic stroke, we used LV‐RNAi targeting Rph3A to decrease its expression and confirmed the disruptive effect of LV‐Rph3A‐RNAi by Western blotting." (PMID 35467084, 2022).
Lambert-Eaton myasthenic syndrome (1 paper, 2023). Lambert-Eaton myasthenic syndrome (LEMS) is an autoimmune, presynaptic disorder of neuromuscular transmission characterized by fluctuating muscle weakness and autonomic dysfunction frequently associated with small-cell lung cancer (SCLC). "SYT2-CMS, SNAP25-CMS, VAMP1-CMS, UNC13A-CMS, RPH3A-CMS, and LAMA5-CMS are characterized by defects in the SNARE complex, and phenotypically similar to Lambert-Eaton myasthenic syndrome (LEMS)." (PMID 36835142, 2023).
memory impairment (1 paper, 2022). "We downregulated Rph3A and found that it further worsened the cerebral infarct, neuronal death and behavioral, cognitive, and memory impairments in rats after MCAO/R." (PMID 35467084, 2022).
pheochromocytoma (1 paper, 2019). "For example, data derived from microarrays and proteomics have shown reduced expression of various components of the regulated secretory pathway (e.g., SNAP25, syntaxin, rabphilin 3A, annexin) in VHL-related pheochromocytomas compared to RET-related pheochromocytomas." (PMID 31390824, 2019).
sarcoidosis (1 paper, 2022). Sarcoidosis is a multisystemic disorder of unknown cause characterized by the formation of immune granulomas in involved organs. "Another possibility may be that the sarcoidosis lesions extended to the posterior pituitary, where they induced inflammation and generation of anti-rabphilin-3A antibodies." (PMID 35292721, 2022).
Stroke (1 paper, 2022). Sudden impairment of blood flow to a part of the brain due to occlusion or rupture of an artery to the brain. "To verify the effects of downregulation of Rph3A on stroke outcome in rats, we examined the sensory, motor, and learning and memory abilities of rats in the adhesive‐removal test, the rotarod test, and the Morris Water maze test, respectively." (PMID 35467084, 2022).
tumor (4 papers, 2022 to 2023). "The expressions of DVL1, MRPL4, and NSUN3 were relatively higher, while that of RPH3A was relatively lower in the tumor tissues." (PMID 36035311, 2022). "Further validation of RPH3A’s involvement in tumor progression was performed using LGG." (PMID 36138874, 2022).
cancer (3 papers, 2022 to 2024). A tumor composed of atypical neoplastic, often pleomorphic cells that invade other tissues. "In addition, the combined meta-analysis identified three additional cancer risk variants (rs77753011 at RPH3A on 12q24, P = 5.5 × 10−15; rs36079339 at AIDA on 1q41, P = 3.9 × 10−10; rs2059904 at EDNRA on 4q31, P = 1.2 × 10−8), of these two were pleiotropic associations." (PMID 37340002, 2023). "Conversely, RGS20, RPH3A, SGCE, and ZDHHC15 exhibited a substantial downregulation in their expression levels within the corresponding cancer cell lines." (PMID 38300336, 2024).
Kidney Disease (3 papers, 2014 to 2022). "They include numerous genes associated with kidney diseases, such as Chga/Chgb, Ptprn, Nphs1/Nphs2, Nsf, Rph3a, Podxl and Cyp11a1." (PMID 36130284, 2022). "Therefore, this review provides an overview of the relevance of Rab GTPases in human diseases, with a special focus on the Rab3a-Rph3A complex and its critical role in kidney disease and a mention of future implications." (PMID 34299299, 2021). "While the ACE-I gene has been very well characterized for many years and associated to UAE and to progression of renal diseases, the role of the RPH3A has not been clarified until recently." (PMID 24918908, 2014).
infection (2 papers, 2017 to 2022). The state of being infected such as from the introduction of a foreign agent such as serum, vaccine, antigenic substance or organism. "The genes that flank the Oas cluster (Dtx1 and Rph3a) were identified as expressed compared to mock-infection in our heatmap." (PMID 28592649, 2017). "Accordingly, Rph3A accumulation at all synaptic connections, as obtained by Rph3A transfection/AAV-mediated infection, prevents the neuron from undergoing cLTP-induced structural modifications at synapses, namely the formation of new dendritic spines." (PMID 35626653, 2022).
neurologic disorders (2 papers, 2017 to 2018). "The condition shows a favorable response to treatment with albuterol sulfate and encourages further research on the role of rabphilin 3a in human neurologic disorders of synaptic transmission." (PMID 29441694, 2018). "In summary, we report a patient with a multisystem neurologic disorder and altered SV regulation attributed to defects in RPH3A, which grants further studies of this gene in human disorders of synaptic transmission." (PMID 29441694, 2018). "In this cohort, seven genes have already been associated with neurological disorders (MNX1, NINJ1, PER2, PHF20, PRSS56, RPH3A, and SBF1) in MalaCards and OMIM." (PMID 28769055, 2017).
neurodegenerative disease (1 paper, 2023). A disorder of the central nervous system characterized by gradual and progressive loss of neural tissue and neurologic function. "RPH3A is involved in presynaptic vesicle trafficking and has been implicated to play a role in synaptic dysfunction in other neurodegenerative diseases." (PMID 37968725, 2023).
RPH3A also shares sentences with these, for which no sentence is quoted: Alzheimer disease (2 papers); Rathke cleft cyst (2); cerebral infarction (1); congenital myasthenic syndrome (1); craniopharyngioma (1); developmental delay (1); glomerular diseases (1); hypophysitis (1); synucleinopathies (1); triple-negative breast carcinoma (1); viral infection (1).